USP5 (ubiquitin specific peptidase 5)
Diseases named in the same sentence as USP5 in open-access papers (continued):
Sharing a sentence is not in itself a finding about the gene and the disease.
tumor (continued). "In vivo experiments showed that combined treatment with chemotherapy drugs and USP5 inhibitors fully suppressed tumor growth." (PMID 36611139, 2023). "After the chi-square test, the expression of USP5 in tumor tissue was higher than that in adjacent tissue, and the difference was statistically significant." (PMID 36611139, 2023). "In keeping with our findings above, Usp5 cKO mice showed better tumor control than WT mice when treated with Trametinib." (PMID 37208329, 2023). "The infiltrating CD8+ T cells and the ratio of CD8+/Treg in the tumor microenvironment were significantly increased in MC38 tumors from Usp5 cKO mice." (PMID 37208329, 2023). "Together, this study describes a molecular mechanism of ERK/USP5-mediated regulation of PD-1 and identifies potential combinatorial therapeutic strategies for enhancing anti-tumor efficacy." (PMID 37208329, 2023). "USP5 inhibition in combination with Trametinib or anti-CTLA-4 has an additive effect on suppressing tumor growth in mice." (PMID 37208329, 2023). "In this experiment, tumor size and weight were obviously increased in mice with USP5 overexpression." (PMID 37492786, 2023). "There is much evidence that USP5 is involved in tumor progression, including promoting the process of tumor epithelial-mesenchymal transition (EMT), stabilizing cyclins to promote proliferation, activating inflammasome, etc.." (PMID 36611139, 2023). "Lastly, our results show that USP5 inhibition combination with Trametinib or CTLA-4 blockade has an additive role in suppressing the tumor growth." (PMID 37208329, 2023). "In contrast with in vitro growth, we observed that USP5 knockdown significantly retarded tumor growth and reduced tumor weight compared with cells expressing Ctrl shRNA." (PMID 34741014, 2021). "The dependence of the malignant phenotype on the presence of both MYCN and USP5 is highlighted by the marked antitumor effects of combination therapy and the low levels of both proteins in treated tumours." (PMID 33658627, 2021). "USP5 also has been shown to be a tumor suppressor in a number of malignant cancers by regulating different proteins." (PMID 34483932, 2021). "USP5 protein levels in tumor tissues was validated by IHC, meanwhile, we also observed significant decrease of PD-L1 and Ki67 levels in USP5 knockdown tumors." (PMID 34741014, 2021). "The increased USP5 expression correlated with large tumor size, poor differentiation, advanced stage and decreased survival." (PMID 34577547, 2021). "Inhibition of USP5 significantly decreased tumor growth and correlated with downregulation of FOXM1, suggesting that USP5 plays a critical role in tumorigenesis and progression of PDA by stabilizing the FOXM1 protein." (PMID 33804240, 2021). "Unexpectedly, a therapeutic combination of an HDAC inhibitor (SAHA) and a novel pyridobenzimidazole (SE486-11) had profound anti-tumour effects and synergistically bound USP5, significantly reducing both USP5 and MYCN levels." (PMID 33658627, 2021). "It has been reported that USP5 promotes tumor proliferation and tumorigenesis through the deubiquitination of histone deacetylase 2 (HDAC2) and β-catenin." (PMID 32477134, 2020). "Depletion of USP5 controls tumor necrosis factor alpha apoptosis-inducing ligand (TRAIL)-mediated apoptotic responsiveness in TRAIL-resistant tumor cells, and this function of USP5 ubiquitination can be blocked by caspase 8-specific inhibitors." (PMID 32268558, 2020). "In the current study, we discovered that USP5 expression level is related to tumor differentiation, CEA and CA19-9 levels." (PMID 33123271, 2020).
tumor (continued). "The results showed that USP5 expression level is related to tumor differentiation, CEA and CA19-9 levels (P< 0.05)." (PMID 33123271, 2020). "Chi-square test indicated that there is a close correlation between USP5 expression and tumor size and FIGO stage (P<0.05)." (PMID 31727867, 2019). "Knockdown of USP5 (#1) led to significant decrease in tumor growth rate of OVCAR3-derived xenografts at the interval between Day 21 and Day 33 after cell transplantation (P<0.001)." (PMID 31727867, 2019). "On Day 33, the xenografts were collected and weighed, which showed that the tumor weight was also reduced by USP5 knockdown (P<0.001)." (PMID 31727867, 2019). "The circHECTD1/miR-1256/USP5 axis exerted its tumor-promoting effects by activating the downstream β-catenin/c-Myc signaling pathway." (PMID 31371702, 2019). "Real-time PCR showed that USP5 amplification was 13.8% of patients when a cut-off was set at 4 copies per tumor cell." (PMID 31727867, 2019). "We further analyzed the effects of USP5 knockdown on the migratory potential of tumor cells using Time-Lapse microscopy and automated tracking of individual cell paths." (PMID 29029505, 2017). "Doxycycline-induced knockdown of USP5 expression significantly attenuated tumor growth compared to control animals, as evidenced by both, external monitoring of tumor growth as well as comparison of final volumes of explanted tumors." (PMID 29029505, 2017). "Second, other oncogenic pathways, such as PI3K‐AKT, may also contribute to tumor progression, and their interactions with USP5 warrant further study." (PMID 40066708, 2025). "Based on our experimental evidence, we propose a mechanistic framework wherein USP5 enhances GPX4 stability by suppressing its ubiquitination-mediated degradation, ultimately diminishing tumor cell susceptibility to ferroptosis and facilitating oncogenic progression." (PMID 40136465, 2025). "Furthermore, RNA interference (RNAi) experiments were performed to knock down USP5 expression, assessing its effects on tumor cell behavior, including proliferation, migration, and invasion, as well as the regulation of mTORC1 and NF‐κB signaling pathways." (PMID 40066708, 2025). "Additionally, USP5 has been shown to facilitate tumor growth in lung cancer through the regulation of the NF‐κB signaling pathway." (PMID 40066708, 2025). "Notably, USP5 expression was predominantly found in tumor epithelial cells, indicating its significant role in this particular cell type." (PMID 40066708, 2025). "USP5 depletion facilitates the transfer of tumor-intrinsic p-STAT1/2 to macrophages." (PMID 41321309, 2025). "Similarly, Cxcl9 and Cxcl10 mRNA expression in murine RAW264.7 macrophages was also increased after coculture with IFN-β–treated Usp5-KO B16 tumor cells." (PMID 41321309, 2025). "Recent evidence suggests that USP5 supports mTOR signaling integrity and facilitates tumor progression, consistent with our findings that suggest USP5 functions as an oncogene, enhancing tumor cell proliferation and metastasis." (PMID 40066708, 2025). "Tumor-intrinsic USP5 impairs CXCL9hi macrophage–mediated antitumor immunity." (PMID 41321309, 2025). "Furthermore, we provide proof-of-concept evidence demonstrating that the inhibition of USP5 with genetic and pharmacological interventions can suppress tumor progression and sensitize tumors to radiotherapy." (PMID 41321309, 2025). "Similarly, in bladder cancer, elevated USP5 expression facilitates tumor progression via stabilization of c-Jun." (PMID 41213937, 2025). "Notably, Fer-1 treatment significantly restored tumor volume and mass in the sgUSP5 group, suggesting that ferroptosis inhibition rescued the growth-suppressive effects induced by USP5 deletion." (PMID 41213937, 2025).
tumor (continued). "Additionally, RNAi‐mediated knockdown of USP5 led to reduced tumor cell activities and downregulation of the mTORC1 and NF‐κB signaling pathways." (PMID 40066708, 2025). "In pancreatic ductal adenocarcinoma (PDAC), USP5 stabilizes FoxM1 to promote tumour growth." (PMID 38229092, 2024). "USP5 expression was higher in tumour tissue than in normal tissue." (PMID 38229092, 2024). "Indeed, knockdown of USP5 expression significantly reduced the tumor-initiating cell frequency by 14.85-fold." (PMID 37726816, 2023). "Furthermore, GO and KEGG enrichment analyses were used to reveal that USP5 co-expressed genes play a critical role in the regulation of spliceosome, RNA splicing, catalytic activity acting on RNA and histone binding in tumor pathogenesis." (PMID 37268697, 2023). "Compared with the control group, apoptosis of MC38 cells was significantly increased in the group of co-culture with Usp5-deficient OT-1 CD8+ T cells, suggesting that knockdown of Usp5 enhances the cytotoxic activity of CD8+ T cells towards MC38 tumor cells in vitro." (PMID 37208329, 2023). "And tumor growth was suppressed in nude mice receiving USP5 knockout transplants." (PMID 37492786, 2023). "Unfortunately, USP5 is aberrantly expressed in human cancers and promotes tumor growth and metastasis, which may limit its application as a target for cancer immunotherapy." (PMID 37932447, 2023). "Accordingly, it could be concluded that the USP5 levels could substantially regulate the proliferation of tumor cells." (PMID 37060095, 2023). "Here the authors identify the ubiquitin-specific protease 5 (USP5) as a deubiquitinase for PD-1 and show that USP5 inhibition in combination with a MEK inhibitor or anti-CTLA-4 could promote anti-tumor immune responses in preclinical models." (PMID 37208329, 2023). "IHC analyses showed that the expression of USP5 in the residual tumors derived from the KrasG12D-shUSP5 was similar to the tumors derived from the control KrasG12D mice in the absence of shUSP5, suggesting that the presence of USP5 expression is most likely responsible for the residual tumor growth." (PMID 36528652, 2022). "Interestingly, some tumor cells activate mechanisms that suppress USP5 inhibition-mediated apoptosis." (PMID 33919439, 2021). "AS can also act as a tumor suppressor in terms of plasticity in cancer; for example, the USP5 isoform 1 can suppress cell proliferation and invasion, whereas the corresponding USP5 stabilizes the chromatin structure and decreases the synthesis of abnormal proteins." (PMID 34445990, 2021). "Furthermore, USP5 expression was upregulated in NSCLC tumor tissues compared with matched adjacent normal tissues." (PMID 34741014, 2021). "As indicated by UALCAN database, the mRNA expression levels of HLA-A, TMEM129, UBE2D1, UBE2N, UBE2T in BCa tissue were significantly increased compared with that in normal tissue; however, the mRNA expression level of USP5 was similar between normal and tumor tissue." (PMID 34776794, 2021). "However, USP5 expression levels were significantly correlated with tumor metastasis in patients with NSCLC." (PMID 32477134, 2020).
tumor (continued). "In this study, we examined USP5 expression in patients with NSCLC and found a negative association between USP5 levels and tumor metastasis in patients with NSCLC." (PMID 32477134, 2020). "USP5 expression levels were significantly correlated with tumor metastasis in patients with NSCLC." (PMID 32477134, 2020). "Among the samples, 61 patients had high expression of USP5 in tumor tissues." (PMID 33123271, 2020). "The higher expressions of USP5 and WT1 are associated with tumour metastasis." (PMID 31845546, 2020). "In addition, USP5 overexpression in BGC823 sh-circHECTD1 cells significantly reversed the inhibitory effects of circHECTD1 knockdown on tumor volume and weight." (PMID 31371702, 2019). "In fact,USP5 itself has been reported to have a tumor inhibiting role in different disease models." (PMID 29029505, 2017). "Furthermore, we also found that Usp5 expression was increased in HCC tissues compared to their adjacent non-tumor tissues." (PMID 28881591, 2017). "However, this process is suppressed by the tumor cell–intrinsic deubiquitinase USP5." (PMID 41321309, 2025). "Notably, the ferroptosis inhibitor Fer-1 partially restores cell growth in USP5 knockout cells, suggesting that USP5 not only acts through classical oncogenic pathways but also regulates the balance between tumor cell survival and death by modulating ferroptosis." (PMID 41213937, 2025). "Therefore, USP5 inhibition may effectively suppress tumor malignancy while promoting antitumor immunity." (PMID 41321309, 2025). "As tumor angiogenesis plays an important role in chemotherapy resistance and anti-angiogenic agents were usually combined with chemotherapeutics in the clinic, we thus assessed whether inhibiting USP5 may enhance the antitumor efficacy of chemotherapy in ESCC." (PMID 40691441, 2025). "In addition, USP5 was positively correlated with tumor grade of TCGA HCC samples." (PMID 37492786, 2023). "Therefore, USP5 is enormously appealing as a strategy for targeted tumor therapy." (PMID 36611139, 2023). "Moreover, the result from single cell sequencing showed that USP5 could regulate several tumor biological behaviors such as apoptosis, DNA damage and metastasis." (PMID 37268697, 2023). "In addition, we observed significant increase of CD8+ and Granzyme B+ positive cells infiltration in USP5 knockdown tumors, indicating USP5 knockdown could activate anti-tumor immune response." (PMID 34741014, 2021). "Moreover, compared with the control group, knockdown of USP5 remarkably decreased tumor sizes." (PMID 34483932, 2021). "In addition, targeting USP5 using shRNA-mediated knock down could reduce PD-L1 protein and triggers anti-tumor immune response." (PMID 34741014, 2021). "Furthermore, knockdown of USP5 in U251 cells remarkably inhibited tumor growth in vivo." (PMID 34483932, 2021). "However, no obvious association was found between USP5 expression and sex, age, tumour differentiation, primary tumour or regional metastatic lymph nodes, respectively." (PMID 31845546, 2020). "As a result of the enhanced antitumor immunity, USP5-IN-1 treatment significantly slowed the growth of CT26 and B16 tumors after irradiation and effectively extended the survival of the tumor-bearing mice." (PMID 41321309, 2025). "In HNSCC, USP5 knockdown led to downregulation of β‐catenin, a key protein in cell adhesion and gene transcription, and upregulation of phosphorylated PTEN, a tumor suppressor." (PMID 40066708, 2025). "To explore the role of USP5 in patient-derived CRC tissues and its influence on ferroptosis in a clinically relevant context, we established CRC organoids from primary tumor samples of a CRC patient." (PMID 41213937, 2025). "This study identifies USP5 as a critical player in HNSCC progression, with overexpression correlating with poor prognosis and enhanced tumor aggressiveness." (PMID 40066708, 2025). "Inhibiting USP5, along with Trametinib or anti-CTLA-4 treatment, shows an additive effect in inhibiting tumor growth in mice." (PMID 40040703, 2025).
tumor (continued). "However, whether USP5 regulates tumor radiosensitivity is unclear." (PMID 39897046, 2025). "By contrast, MSK1 is highly activated in malignant CRC cells, and activated MSK1 can increase Snail protein stability by enhancing USP5-mediated Snail deubiquitination, with the resulting high Snail expression being able to promote EMT and tumor metastasis." (PMID 40164688, 2025). "Our results suggested that USP5 is overexpressed in NSCLC tissues and cell lines, and this high expression is significantly correlated with tumor size and patient survival." (PMID 36611139, 2023). "Finally, USP5 could inhibit ferroptosis through DUB LSH to promote tumor progression." (PMID 37492786, 2023). "Collectively, these results demonstrate that co-targeting USP5 and ERK signaling has an additive effect on reducing PD-1 and suppressing tumor growth in different preclinical tumor models." (PMID 37208329, 2023). "To investigate the function of USP5 for GBM growth in vivo, we established orthotopic tumor models by intracranially implanting U251-shNC and U251-shUSP5#3 cells into nude mice." (PMID 34483932, 2021). "Our own results demonstrate that USP5 is overexpressed on the mRNA level in the majority of PDAC cases and plays a tumor-promoting role in vitro and in vivo." (PMID 29029505, 2017). "We conducted extensive structure-activity relationship studies on WP1130, a Usp5/Usp9x/Usp14/UCH-L1/UCH-L5 inhibitor, to improve its safety, solubility and anti-tumor activity in mice." (PMID 24980819, 2014). "We have found that the use of the USP5 inhibitor EOAI3402143, especially when combined with chemotherapy agents 5-FU and CDDP, can significantly suppress angiogenesis and tumor growth, and this therapeutic strategy has superior efficacy compared with 5-FU/CDDP alone." (PMID 40691441, 2025). "The Usp5-WT or -KO murine tumor cells were exposed to radiation or not, and USP5 depletion did not affect cell growth and viability in vitro." (PMID 41321309, 2025). "However, USP5 facilitates the degradation of YBX3, leading to the stabilization of SLC7A11 and thereby promoting CRC cell survival and tumor progression." (PMID 41213937, 2025). "USP5 has been reported as a typical tumor promoter, as it not only stabilizes oncoproteins to promote cancer metastasis but also contributes to treatment resistance in tumors." (PMID 41321309, 2025). "By integrating analysis of CUT&Tag and RNA sequencing data, we identified ubiquitin-specific protease 5 (USP5) as a Notch-signaling downstream effector that is transcriptionally upregulated by the NOTCH1 intracellular domain (NICD1)–RBPJ complex and mediates tumor angiogenesis." (PMID 40691441, 2025). "USP5, a deubiquitinating enzyme (DUB) involved in inflammatory responses that is highly expressed in primary CRC tissues and promotes tumorigenesis by stabilizing tumor proteins, was identified in our study as a novel DUB of STAT3." (PMID 41281755, 2025). "Collectively, these findings demonstrate that USP5 depletion sensitizes CRC cells to ferroptosis and suppresses tumor progression in both patient-derived organoid and in vivo xenograft models, highlighting the USP5/YBX3-ferroptosis axis as a potential therapeutic target in CRC." (PMID 41213937, 2025). "Moreover, USP5 21, USP18107, and USP47 116 suppress Snail degradation to induce EMT, thereby promoting CRC cell migration and tumor metastasis in vitro and in vivo." (PMID 41208892, 2025). "Mechanistically, ANXA1 promotes the binding of USP5 to GOT1, thus preventing the degradation of GOT1 via the ubiquitin-proteasome pathway and promoting glutamine metabolism to enhance the oxidative stress adaptation of tumor cells and promote tumor growth." (PMID 40390008, 2025). "Moreover, combined treatment with EOAI34 (a USP5 inhibitor) and trametinib (a MEK inhibitor) in CT26 tumor-bearing mice slowed tumor growth and increased CD8+ T-cell infiltration." (PMID 38715050, 2024).